Y_RNA (Y RNA )
Gene: Miscellaneous RNA gene on chromosome 20 (29,575,060 to 29,575,171, forward strand). Ensembl gene ENSG00000283592.
Homologues: Orthologues: chimpanzee Y_RNA (98% identical), macaque Y_RNA (90% identical). Paralogues in human: Y_RNA (99% identical), Y_RNA (98% identical), Y_RNA (97% identical), Y_RNA (96% identical), Y_RNA (87% identical), RNY1P5 (86% identical), Y_RNA (86% identical), Y_RNA (85% identical), Y_RNA (84% identical), Y_RNA (83% identical), RNY1 (82% identical), Y_RNA (82% identical), and 100 more.